FOXP3 (forkhead box P3)
Diseases named in the same sentence as FOXP3 in open-access papers (continued):
Sharing a sentence is not in itself a finding about the gene and the disease.
COVID-19 (continued). "Evidence of T-cell dysregulation demonstrated by immunohistochemical paucity of FOXP3+, Tbet+ and LEF1+ positive T-cells and a downregulation of key genes responsible for T-cell crosstalk, maturation and migration as well as a reactivation of herpes viruses in 6 COVID-19 lymph nodes (EBV, HSV)." (PMID 34966385, 2021). "Moreover, regulatory T (Treg) lymphocytes play a vital role in suppressing excessive immune responses to pathogens; however, the molecular mechanisms involved in the regulation of forkhead box P3 (FOXP3) expression and antigen-specific response of Treg cells in COVID-19 are unclear yet." (PMID 34225645, 2021). "Furthermore, the hypoxic environment in the lung of severe COVID-19 patients may activate HIF-1α, which mediates aerobic glycolysis, and thereby promotes the degradation of FOXP3 proteins." (PMID 33178221, 2020). "However, in severe COVID-19 patients, those CD25+ T-cells are considered to be vigorously proliferating, whilst becoming multifaceted effector T-cells or dying, instead of maturing into FOXP3+ Tregs." (PMID 33178221, 2020). "By analyzing single cell transcriptomes, we demonstrate that CD4+ T-cells in severe COVID-19 have an impaired FOXP3-mediated negative feedback, generating CD25+ hyperactivated T-cells, which show multifaceted effector T-cell differentiation and uniquely produce the protease Furin." (PMID 33178221, 2020). "Collectively, CD4+ T-cells from severe COVID-19 patients are hyperactivated and FOXP3-mediated negative feedback mechanisms are impaired in the lung, which may promote immunopathology." (PMID 33178221, 2020). "Furthermore, in the recovered COVID-19 subjects with low antibody levels, their spike-specific CD4 T cells showed very little proliferative response in vitro, and in the small number of cells that did proliferate, they appeared to relatively highly express the Treg transcription factor Foxp3." (PMID 36544780, 2022). "In some COVID-19 patients without Foxp3, the levels of CD45RA+CCR7+ Tregs in some COVID-19 patients decreased, while the levels of activated CD45RA-CCR7+ Tregs increased." (PMID 36034704, 2022). "Additionally, the CD4+ FOXP3+ Tregs of the lung and PBMC showed a rising trend on day five after infection in the nonhuman model of COVID-19 pathogenesis." (PMID 36992283, 2023). "In addition, on 5 days post-infected (dpi), the CD4+ FOXP3+ Tregs of lung and PBMC exhibited an increasing trend in the nonhuman primate model of COVID-19 progression." (PMID 35874688, 2022). "Moreover, some COVID-19 patients showed a reduction in the levels of CD45RA+CCR7+ Tregs and an increase in the levels of activated CD45RA-CCR7+ Tregs, in the absence of Foxp3." (PMID 34631206, 2021). "Additionally, Foxp3 alone is not always sufficient to correctly identify Tregs, suggesting that a range of markers and higher dimensional approaches (such as UMAP) are needed to fully separate Tregs from non-Tregs in the context of the aggressive cellular activation seen in COVID-19 patients." (PMID 36669118, 2023).
inflammatory bowel disease (72 papers, 2008 to 2026). A spectrum of small and large bowel inflammatory diseases of unknown etiology. "Immune homeostasis in the intestine is tightly controlled by FOXP3+ regulatory T cells (Tregs), defects of which are linked to the development of chronic conditions, such as inflammatory bowel disease (IBD)." (PMID 33929751, 2021). "Bamidele and colleagues looked at the interaction of EZH2 and FOXP3 in inflammatory bowel disease and found that a mutation in FOXP3 disrupted EZH2 recruitment and its co-repressive function." (PMID 33800594, 2021). "Inflammatory bowel disease is associated with the accumulation of FOXP3+ T cells and these cells have been found to preferentially express IL-17 or IL-17 in combination with TNF-α." (PMID 29593749, 2018). "Failure of the IL-10R signaling pathway in Tregs has also been associated with loss of FoxP3 expression and inflammatory cytokine release in a murine model of inflammatory bowel disease." (PMID 28396319, 2017). "Moreover, succinate accumulation has been linked to immune dysregulation, including FOXP3 destabilization and Treg dysfunction in inflammatory bowel disease." (PMID 41550731, 2026). "Maintaining the properties of Foxp3(+) regulatory T cells (Tregs) has been found to be essential for controlling the immune response in the gut, and the imbalance between Tregs and T effector cells has been linked to inflammatory bowel disease." (PMID 37291580, 2023). "Furthermore, genetic variants in interleukin-10 (IL-10), IL-10 receptor(IL-10R), X-linked inhibitor of apoptosis protein (XIAP), and forkhead box P3 (FOXP3) have been linked to very early-onset inflammatory bowel disease (VEOIBD)." (PMID 34956195, 2021). "Maintaining the identity of Foxp3+ regulatory T cells (Tregs) is critical for controlling immune responses in the gut, where an imbalance between Tregs and T effector cells has been linked to inflammatory bowel disease." (PMID 26583087, 2015). "Indeed, regulatory CD4+CD25+Foxp3+ T cells are abundant in the colonic mucosa, and breakdown of these local mechanisms of immune regulation and gut homeostasis has been associated with the development of inflammatory bowel diseases (IBD)." (PMID 35919733, 2021). "Several cytokines are essential to maintain tolerance to the gut microbiota, as evidenced by the association of IL-10, FoxP3 or TGFβ1 function in mice or humans with inflammatory bowel disease (IBD) or autoinflammatory disorders." (PMID 22624013, 2012). "Beyond EAE, Th17-derived ER-Tregs — combining stable Foxp3 expression, robust tissue persistence, and potent suppression — hold promise for other Th17-driven diseases such as inflammatory bowel disease." (PMID 40762956, 2025). "Patients with Inflammatory Bowel Disease are known to have selective loss of IL10 secretion from Tr1 cells, while IL10 production from FOXP3+ Tregs appears unaffected, further emphasizing a specific importance of Tr1s to IBD." (PMID 37654482, 2023). "For example, IL-17+ Foxp3+ T cells have been observed in patients with inflammatory bowel disease, or more specifically, in patients with Crohn’s disease but not ulcerative colitis." (PMID 32391008, 2020). "Similarly, a mutation in FOXP3 gene is associated with spontaneous development of inflammatory bowel disease (IBD) and a phase 1 clinical trial of Treg therapy in patients with refractory Crohn's disease was found to be effective." (PMID 31024539, 2019). "Based on these observations, in vivo expansion of Foxp3+ Tregs using IL-2 and other methods has been explored as a potential therapeutic for human inflammatory bowel disease (IBD)." (PMID 30930900, 2019). "When equally active in humans, a rationale is provided to develop GC-mimicking therapeutic strategies which specifically target Foxp3+ Treg cells for the treatment of inflammatory bowel disease." (PMID 30936873, 2019).
inflammatory bowel disease (continued). "A clinical trial of in vitro-expanded naïve Tregs is also underway in Crohn’s Disease, the first application of FOXP3+ Treg immunotherapy for inflammatory bowel disease (IBD) (ISRCTN97547683)." (PMID 29163527, 2017). "RA-producing DC are immunosuppressive and therapeutic in animal models of inflammatory bowel disease and their efficacy rests on RA-mediated differentiation of Foxp3+ Tregs." (PMID 24465383, 2014). "Paeoniflorin, a monoterpene glycoside extracted from the roots of Paeonia lactiflora, can significantly promote the differentiation of CD4+CD25+Foxp3+ Tregs and suppress the production of Th17 cells, restoring the Th17/Treg balance for the treatment of inflammatory bowel disease (IBD)." (PMID 41458964, 2025). "Since CD4+CD25+FoxP3+ Treg lymphocytes have been described to play an important role in the development and control of inflammatory bowel disease, we next analysed the representation of this population in the spleen and the MLNs of the different groups of animals after in vitro stimulation." (PMID 39769391, 2024). "When wild type or BMPR1α-deficient Treg cells, expressing high levels of Foxp3, were co-transferred to lymphopenic mice, with naive conventional CD4+ T cells, only wild type Treg cells retained Foxp3 expression, and were able to protect recipient mice from inflammatory bowel disease." (PMID 35418975, 2022). "Despite the elevated pool of T lymphocytes in the mucosa of patients with inflammatory bowel disease (IBD), the active disease associates with diminished anti-inflammatory forkhead box P3 CD4-positive regulatory T cells (FOXP3+CD4+ Tregs) in the peripheral blood." (PMID 36140736, 2022). "The results of a multicenter phase I/IIa clinical trial indicate that the change in the balance between Foxp3 + CD4 + Treg cells and T effector cells in the intestinal microenvironment may be the cause of inflammatory bowel disease." (PMID 33553436, 2021). "Here we investigate how a pleiotropic cytokine interleukin (IL)-15 may modify the functional commitment of CD4+ T cells expressing the lineage-associated transcription factors: forkhead box P3 (Foxp3; Treg) and RORγt (Th17) in the context of inflammatory bowel disease (IBD)." (PMID 26964669, 2016). "However, FOXP3+ T cells are paradoxically increased in the intestines of patients with the inflammatory bowel disease (IBD) ulcerative colitis (UC) or Crohn’s disease (CD)." (PMID 26305224, 2015). "Interestingly, IL-17-producing Foxp3+CD4+ lymphocytes are also observed in inflammatory bowel disease (IBD) patients." (PMID 26734006, 2015). "Furthermore, the authors demonstrated that CD4+CD25+ Tregs with FOXP3 transduction inhibited the proliferation of lymphocytes and the occurrence of inflammatory bowel disease and gastritis in mice." (PMID 24944616, 2014). "Also, in human CD4 T cells from healthy donors, inflammatory bowel disease and RA patients, it results in increased number of FOXP3-expressing cells, however, induction of FOXP3 expression versus preferential expansion of containing Treg has not been dissected." (PMID 37741949, 2023). "In addition, the incidence of allergy and inflammatory bowel disease (IBD), which together cause IPEX syndrome (immune dysregulation polyendocrinopathy enteropathy X-linked (IPEX) syndrome), is caused by dysfunction in FOXP3+ T cells." (PMID 36591309, 2022). "The formal proof that such polyclonal anergy-derived Foxp3+ Treg cells could be protective was obtained by usingin vivo models of inflammatory bowel disease and autoimmune arthritis in which the adoptive transfer of anergy-derived Foxp3+ Treg cells suppressed disease development." (PMID 30613389, 2018). "However, IL-17+FOXP3+ cells were identified in inflamed intestinal mucosa of patients with Crohn's disease (CD), but not in patients with ulcerative colitis (UC), the two clinical manifestations of inflammatory bowel disease." (PMID 23592971, 2013).
inflammatory bowel disease (continued). "As an example, in a mouse animal model of inflammatory bowel disease (IBD), the beneficial effect of injected human adipose derived MSCs (hASCs) on the clinical and histological scores of mice was associated with an increased number of CD4+CD25+Foxp3+ and CD4+IL10+ cells in the lymph nodes." (PMID 23734780, 2013). "Hookworm-derived recombinant proteins AIP-1 and AIP-2 have been shown to reduce inflammation in mouse models of inflammatory bowel disease and inflammatory airway disease by inducing CD4+Foxp3+ cells and IL-10 production." (PMID 38239430, 2023). "Importantly, using a valid animal model of inflammatory bowel disease (IBD), we demonstrated that CQ promotes Foxp3 expression and differentiation of TREG cells in a Nurr1-dependent manner, leading to significant improvement of IBD-related symptoms." (PMID 31664129, 2019). "Ectopic expression of FOXP3 in CD4+CD25− T cells may endow CD4+CD25− T cells with Treg-like suppressive capability to prevent inflammatory bowel disease (IBD) and autoimmune gastritis." (PMID 26441996, 2015). "Here we show that CD4+Foxp3+Tregs produce the effector cytokine IL-17A during oropharyngeal candidiasis (OPC) and inflammatory bowel disease in a TLR-2/Myd88 signaling dependent manner." (PMID 25790134, 2015). "We found that B. infantis mediated Foxp3 expression through PD-1/PD-L1 pathway, which promoted Tregs differentiation and improved IL-10 and TGF- β 1 expression, so as to reduce the immune and inflammatory response of mice with inflammatory bowel disease." (PMID 35860248, 2022). "Additionally, the administration of probiotics in different animal models improved inflammatory bowel disease, atopic dermatitis, and RA, probably as a result of enrichment of CD4+Foxp3+ Tregs in inflamed body areas." (PMID 27553386, 2016). "In inflammatory bowel disease (IBD), the expression of CD39 in the FoxP3+ Treg immunophenotype is reduced, whereas an increase in CD39 expression is associated with a positive response to treatment." (PMID 32488850, 2020). "In patients diagnosed with inflammatory bowel disease (IBD), plasma succinate levels exhibited a significant negative correlation with FOXP3 expression." (PMID 41476741, 2025).
atherosclerosis (70 papers, 2007 to 2025). A disease characterized by the build-up of fatty material and calcium deposition in the arterial wall resulting in partial or complete occlusion of the arterial lumen. "These cells are regulated by FOXP3, and recently, genetic variants of the FOXP3 gene have been identified as risk factors for the development of atherosclerosis." (PMID 40076974, 2025). "For example, the Treg/Th17 imbalance is associated with atherosclerosis and acute coronary syndrome and is regulated by FOXP3/STAT5 and RORγt/STAT3 transcription factors, respectively." (PMID 37763334, 2023). "We found that Dnmt3b silencing ameliorated atherosclerosis was associated with increasing the Treg levels caused by reducing the methylation levels of Foxp3-TSDR and upregulated the expression of Foxp3 in Tregs." (PMID 35422896, 2022). "Our further investigation showed that elevated methylation levels of FOXP3 are associated with atherosclerosis by reducing the percentages of Tregs." (PMID 35422896, 2022). "Depletion of FoxP3+ Tregs exacerbated atherosclerosis, but was also associated with higher plasma levels of atherogenic lipoprotein." (PMID 33805071, 2021). "Several studies support Foxp3-positive regulatory T cells (Tregs) as inhibitors of atherosclerosis; however, the mechanism underlying this protection remains elusive." (PMID 31314754, 2019). "In an animal experiment, cytokine therapy with IL-2/anti-IL-2 monoclonal antibody complexes could attenuate the development and progression of atherosclerosis by increasing CD4+CD25+Foxp3+ regulatory T cells in apolipoprotein E-deficient mice." (PMID 36299596, 2022). "However, Tregs show the loss of FOXP3 expression and immunosuppressive function during atherosclerosis progression, owing to which a fraction of these cells is transformed into follicular Th cells, which are proatherogenic." (PMID 36304068, 2022). "We demonstrated that DNMT3b accelerated atherosclerosis may be associated with FOXP3-TSDR hypermethylation, which is responsible for the subsequent down-regulation of FOXP3 expression and inhibition of Treg function." (PMID 35422896, 2022). "DNMT3b accelerated atherosclerosis, and may be associated with FOXP3 hypermethylation status in regulatory T cells." (PMID 35422896, 2022). "We also found that the FOXP3 transcript expression in blood is associated with Treg content, but contrarily to the studies performed in children, we cannot associate this marker with other systemic inflammation parameters or with subclinical atherosclerosis." (PMID 32210181, 2020). "Thus, we hypothesize that DNMT3b-mediated hypermethylation of FOXP3 in Tregs would be one of the underlying mechanisms of atherosclerosis." (PMID 35422896, 2022). "In mice with advanced atherosclerosis, Foxp3, Ifng, Il21, and Pdcd1 mRNA levels were increased in the splenic CD3+ cells indicating that atheroprogression drives T-cell activation and regulatory transcriptional programs." (PMID 38270847, 2024). "FOXP3 is an immunoregulatory DNA-binding protein that is vital in the development and function of Tregs, and the DNMT3B-mediated downregulation of FOXP3 induces atherosclerosis." (PMID 37947606, 2023). "A similar study in an atherosclerosis model likewise showed that FoxP3-specific T-cell responses substantially decreased the number of FoxP3+ Tregs, resulting in increased atherosclerotic lesion formation." (PMID 36175673, 2023). "Our recent studies showed that CD4+LAP+ and CD4+CD25+ Tregs are suppressed in ACS and that CD4+LAP+ and CD4+CD25+Foxp3+ T cells induced by nasal-oxidized low-density lipoprotein suppress effector T cell responses and attenuate atherosclerosis in ApoE−/− mice." (PMID 36405994, 2022).